VEGFA (vascular endothelial growth factor A)
Diseases named in the same sentence as VEGFA in open-access papers (continued):
Sharing a sentence is not in itself a finding about the gene and the disease.
Vestibular schwannoma (10 papers, 2013 to 2025). A vestibular schwannoma (also known as acoustic neuroma, acoustic neurinoma, or acoustic neurilemoma) is a benign, usually slow-growing tumor that develops from the VIIIth cranial nerve supplying the inner ear. "During vestibular schwannoma progression, a distinct type of Schwann cells was identified, marked by overexpression of VEGFA, which showed enhanced abilities in proliferation, migration, and differentiation, contributing to significant functional and morphological recovery." (PMID 40629113, 2025).
adenoid cystic carcinoma (9 papers, 2012 to 2025). A malignant tumor arising from the epithelial cells. "Pathway analysis of the 115 hypermethylated downregulated TSGs indicates that these genes are enriched in several cancer-relevant pathways including hematopoietic stem cell gene regulation, VEGFA-VEGFR signaling pathway and adenoid cystic carcinoma." (PMID 34588438, 2021).
atopic dermatitis (9 papers, 2012 to 2023). "Mechanistically, exosomal microRNA-147a repressed pathological angiogenesis and inflammatory injury during atopic dermatitis progression by targeting VEGFA and MEF2A-TSLP axis." (PMID 37264030, 2023). "microRNA-147a-overexpressing adipose-derived stem cells-derived exosomes suppressed pathological angiogenesis and inflammatory injury in atopic dermatitis by targeting VEGFA and MEF2A-TSLP axis." (PMID 37264030, 2023).
brain glioma (9 papers, 2017 to 2025). A malignant glioma that involves the brain. "In brain glioma, LINC01116 regulates VEGFA expression through competitive absorption of miR-31-5p." (PMID 33762953, 2021).
chordoma (9 papers, 2014 to 2025). Chordomas are rare malignant tumors arising from embryonic remnants of the notochord in axial skeleton. "In addition, one previous study established a nomogram to predict the prognosis of chordoma patients according to the clinical characteristics and immunohistochemistry, including the extent of resection, E-cadherin, Ki-67, and VEGFA." (PMID 36158641, 2022).
cystic fibrosis (9 papers, 2012 to 2025). Autosomal recessive disorder caused by pathogenic variants in the CFTR gene (cystic fibrosis transmembrane conductance regulator), which encodes a chloride and bicarbonate channel expressed in epithelial cells, and follow the diagnosis criteria. "Prominent examples of trials on protein replacement therapy are expression of cystic fibrosis transmembrane regulator protein in cystic fibrosis and vascular endothelial growth factor A (VEGF-A)." (PMID 33912824, 2021).
gynecological cancers (9 papers, 2019 to 2025). "Consistent with a chronic inflammatory state, VEGF signaling and VEGFA expression were upregulated in HRD tumors, expanding prior findings in BRCA1-deficient murine ovarian models to a broader spectrum of HRD and gynecological cancers 9,87." (PMID 41279139, 2025). "In gynecologic cancers, common genes regulated by prognosis-alternative miRNAs such as BCL2, EGFR, PDGFRA, and VEGFA were also demonstrated to be combinational targets for anti-cancer drugs." (PMID 32523951, 2020).
hantavirus infection (9 papers, 2012 to 2020). "In the current SFTS patients, a prolonged high level of VEGFA in the recovery period may indicate the sustained vascular angiogenesis and repairmen, similar with hantavirus infection, also from the Bunyaviridae." (PMID 28806760, 2017).
Headache (9 papers, 2018 to 2026). Cephalgia, or pain sensed in various parts of the head, not confined to the area of distribution of any nerve. "This is the first study to show that VEGFA rs3025039 is associated with headache in AMS." (PMID 32718338, 2020). "Meanwhile, VEGFA-rs3025039 was associated with AMS-related headaches." (PMID 32718338, 2020).
hyperuricemia (9 papers, 2018 to 2025). An abnormally high level of uric acid. "Furthermore, hyperuricemia suppresses vascular endothelial growth factor-A (VEGFA) by negatively regulating miR-92a, thereby increasing Kruppel-like factor 2 (KLF2) expression, which impairs endothelial cell proliferation and repair capacity." (PMID 41166265, 2025).
leiomyosarcoma (9 papers, 2008 to 2021). An uncommon, aggressive malignant smooth muscle neoplasm, usually occurring in post-menopausal women. "In contrast to PTSMT, leiomyosarcomas show generally higher expression of VEGFA than leiomyomas." (PMID 24398114, 2014). "In leiomyosarcoma-derived cell lines it could be demonstrated that hepatocyte growth factor (HGF) induces a decrease in anti-angiogeneic THBS1 and an increase in VEGFA." (PMID 24398114, 2014).
necrotizing enterocolitis (9 papers, 2016 to 2025). Necrotizing enterocolitis (NEC) is a devastating disease that affects mostly the intestine of premature infants. "In cases of neonatal necrotizing enterocolitis, miR-429/200a/200b and miR-141/200c clusters were found to negatively regulate VEGFA, increasing its expression." (PMID 35992774, 2022). "In conclusion, this is the first study to show differences in DNA methylation of TLR4, VEGFA, and DEFA5 in infants affected by necrotizing enterocolitis." (PMID 33748044, 2021).
parasitic infections (9 papers, 2010 to 2025). "Nevertheless, these findings raised the possibility that the alternatively polarized macrophage-produced FLT1 can contribute to the defense response of the host against the parasite infection through VEGFA neutralization and angiogenesis inhibition." (PMID 37215144, 2023).
prostate adenocarcinoma (9 papers, 2013 to 2024). "Cancer type details of overexpressed genes indicated that ANGPLT4, P4HA1, and VEGFA were mostly mutated in prostate adenocarcinoma and prostate neuroendocrine carcinoma." (PMID 37048688, 2023). "Pre-clinical data have shown that shutting down tumor vasculature via acute inhibition of vascular endothelial growth factor A signal transduction in mice bearing PC-3 human prostate adenocarcinoma xenografts leads to a reduction in the tumor Ktrans values." (PMID 39120366, 2024). "Further, The Cancer Genome Atlas data (TCGA) independent database was used for validation of key genes EGFR, MYC, VEGFA, PTEN expression in prostate adenocarcinoma." (PMID 35456461, 2022).
benign ovarian tumors (8 papers, 2000 to 2025). "It was shown that, compared with benign ovarian tumor tissue, malignant cancer tissues demonstrated a significantly higher expression of VEGFA, which is considered an unfavorable prognostic factor." (PMID 36230822, 2022).
cerebral malaria (8 papers, 2008 to 2025). A sequestration of Plasmodium falciparum in the brain, which can cause coma and/or seizures. "Together with vascular signaling (VEGFA-VEGFR2), platelet activation and coagulation, and neutrophil activation, these are adaptive processes during the late stages of cerebral malaria, which may turn maladaptive and pathological." (PMID 39151016, 2024). "Additionally, post-mortem brain tissue from severe cerebral malaria patients presented no changes in HIF-1α expression but increases in VEGFA, indicating changes in VEGFA may be tissue-dependent or HIF-independent." (PMID 37375100, 2023).
giant cell arteritis (8 papers, 2007 to 2025). "MiR-93 was dysregulated and may be involved in the regulation of vascular endothelial growth factor A (VEGF-A) expression in the pathogenesis of acute KD-induced arteritis." (PMID 36003919, 2022).
hypercoagulability (8 papers, 2017 to 2025). "This study found that genotypes of seven thrombophilia genes, including MTHFR, SERPINE1, MTR, ANXA5, MTRR PROZ, and VEGFA, are associated with inherited thrombophilia risk for RPL-RIF." (PMID 39498089, 2024).
insulinoma (8 papers, 2010 to 2023). "This conforms with what was previously observed in RIP-Tag2 insulinomas, in which VEGFA-dependent angiogenesis was reduced by absence of the Shb gene but compensated for by other mechanisms, such as “inflammation”." (PMID 29721156, 2018).
nephritis (8 papers, 2007 to 2025). Inflammation of renal tissue. "Our study also found that VEGFA expression increased along with ECs proliferation on the 7th day of anti‐Thy‐1 nephritis." (PMID 33987885, 2021). "Our results indicated that VEGFA expression increased significantly in the mesangial area of anti‐Thy‐1 nephritis." (PMID 33987885, 2021). "Among them, VEGFA is the main contributor to the development of new blood vessels, and it is also a proinflammatory cytokine, which is closely related to kidney inflammation." (PMID 34164430, 2021). "Therefore, we suspected that MCs‐derived VEGFA and ECs‐derived Angpt2 might play important roles in ECs proliferation of anti‐Thy‐1 nephritis." (PMID 33987885, 2021). "The key targets such as TNF, VEGFA, PTGS2, MMP9, and MAPK1 are directly or indirectly related to the 7 phenolic acids and multiple nephritis-related pathways." (PMID 36998608, 2023). "The protein interaction analysis network showed that TNF, VEGFA, PTGS2, MMP9, MAPK1, and other proteins were the key targets of the 7 phenolic acids in the treatment of nephritis." (PMID 36998608, 2023). "The docking results between the targets of VEGFA and MMP9 and each component were also good, which may play an essential role in preventing as well as treating nephritis." (PMID 36998608, 2023).
Oral ulcer (8 papers, 2017 to 2026). Erosion of the mucous mebrane of the mouth with local excavation of the surface, resulting from the sloughing of inflammatory necrotic tissue. "This study will analyze the clinical outcome, angiogenesis, and expression of FGF-2 and VEGFA in the oral ulcer rat model after AdMSCM oral gel application." (PMID 36963426, 2024). "This investigation reveals that the topical application of AdMSCM oral gel is able to enhance the clinical outcome, angiogenesis, and expression of VEGFA and FGF-2 in the oral ulcer animal model (R. novergicus)." (PMID 36963426, 2024). "This study will confirm whether the application of AdMSCM oral gel can enhance the expression of VEGFA and FGF-2, angiogenesis, and clinical outcome in oral ulcer rat models." (PMID 36963426, 2024).
Peri-Implantitis (8 papers, 2017 to 2025). An inflammatory process with loss of supporting bone in the tissues surrounding functioning DENTAL IMPLANTS. "Genetic analyses performed by array CGH on subjects affected by peri-implantitis revealed the amplification of the gene encoding VEGFA." (PMID 31242601, 2019).
peripheral vascular disease (8 papers, 2009 to 2025). Any disorder affecting blood flow through the veins or arteries outside of the heart. "And higher levels of vascular endothelial growth factor A (VEGF-A) in EVs play important roles in T2D-related peripheral vascular disease." (PMID 33551993, 2020).
psoriasis plaque (8 papers, 2006 to 2024). "Among the different forms of psoriasis, plaque psoriasis is most strongly associated with VEGFA." (PMID 38203230, 2023).
congenital heart disease (7 papers, 2021 to 2025). "Moreover, the overexpression of vascular endothelial growth factor A, soluble FMS-like tyrosine kinase-1 (sFlt-1), and soluble endocrine in fetuses with congenital heart disease were observed in their heart tissue and cord blood." (PMID 36233829, 2022).
goiter (7 papers, 2010 to 2023). Enlargement of the thyroid gland usually caused by lack of iodine in the diet, hyperthyroidism, or thyroid nodules. "A comparison between tumor and colloid goiter and between tumor-adjacent tissue and goiter-adjacent tissue revealed a significantly higher expression of the VEGFA gene in the samples of colloid goiter and its adjacent tissue." (PMID 32824922, 2020). "Tumors, despite showing lower VEGFA mRNA expression, presented higher VEGFA protein levels compared to goiter tissue." (PMID 32824922, 2020). "We found higher levels of VEGFA and NFE2L2 transcripts and the VEGFA protein in goiter and PTC samples than in normal tissue." (PMID 32824922, 2020). "A comparison of VEGFA levels between tumor and goiter samples showed significantly higher expression in the tumor, a result suggesting a relation at the protein level opposite to that we observed in mRNA levels." (PMID 32824922, 2020). "The protein levels of VEGFA were higher in the tumor compared to those in normal tissue (p = 0.0009), the goiter (p = 0.0222), and goiter-adjacent tissue (p = 0.0003)." (PMID 32824922, 2020). "Besides eliminating vascular remodeling and inhibiting hair follicle hypertrophy, blocking VEGFA inhibits hyperthyroidism by increasing lymphatic flow in the Graves thyroid gland, decreasing thyroid weight during goiter development." (PMID 37859983, 2023). "Comparisons between the groups revealed that VEGFA gene expression was higher in the goiter than in the tumor (RQ median = 20.28 vs. 1.5; p < 0.0001) and also in the goiter-adjacent tissue than in the tumor-adjacent tissue (RQ median = 20.72 vs. 3.40, p < 0.0001)." (PMID 32824922, 2020). "The expression of VEGFA was upregulated in the goiter compared to the normal tissues (p = 0.0397)." (PMID 32824922, 2020). "This increase in the expression of the VEGFA gene in goiter may be due to several factors." (PMID 32824922, 2020). "VEGFA and NFE2L2 also showed elevated expression in the tumor- and goiter-adjacent tissues." (PMID 32824922, 2020). "VEGFA and NFE2L2 showed high expression levels in the tumor and goiter." (PMID 32824922, 2020).
ischemic cardiomyopathy (7 papers, 2020 to 2025). Ischemic cardiomyopathy is a cardiomyopathy in which a weakness in the muscle of the heart due to inadequate oxygen delivery to the myocardium with coronary artery disease being the most common cause. "The expression values of VEGFA from GSE9128 in the control group were higher compared to the Ischemic cardiomyopathy (ICM) group, coincident with early research that increased the expression of VEGFA might be a potential therapeutic method for ICM." (PMID 37880698, 2023).
mantle cell lymphoma (7 papers, 2010 to 2022). Mantle cell lymphoma is a rare form of malignant non-Hodgkin lymphoma affecting B lymphocytes in the lymph nodes in a region called the ``mantle zone''. "Moreover, rituximab, a B cell-targeted monoclonal antibody that has become the first-line therapy in IMN according to KDIGO CLINICAL PRACTICE GUIDELINE ON GLOMERULAR DISEASES 2021, showed its ability to decrease the VEGFA level in plasma in patients with recurrent mantle cell lymphoma." (PMID 36114523, 2022).
pulmonary sarcoidosis (7 papers, 2009 to 2025). Sarcoidosis affecting the lung parenchyma. "Both VEGFA and HIF1A are associated with susceptibility and progression of COPD with HIF1A, they also play important roles in pulmonary sarcoidosis and acute lung injury." (PMID 30700303, 2019).
Tetralogy of Fallot (7 papers, 2009 to 2024). A congenital cardiac malformation comprising pulmonary stenosis, overriding aorta, ventricular septum defect, and right ventricular hypertrophy. "Single nucleotide polymorphisms of VEGFA, such as c.-2578C>A, c.+963C>T, c.-634C>G, c.-1154G>A and c.-460T>C, were associated with an increased risk of developing CHDs, especially for tetralogy of Fallot and ventricular septal defects." (PMID 37238360, 2023).
Abdominal obesity (6 papers, 2016 to 2024). Excessive fat around the stomach and abdomen. "In addition, genetic determinants of abdominal obesity have been shown to attenuate weight loss after dietary intervention with special attention paid to the rs1358980-T risk allele in the VEGFA locus." (PMID 34048505, 2021).
airway hyperresponsiveness (6 papers, 2005 to 2024). "IL-6, VEGFA, and AHR interact to induce eosinophilic airway inflammation, mucinous metaplasia, subepithelial fibrosis, myocyte proliferation, and dendritic cell activation, leading to airway hyperresponsiveness and angiogenesis of airway remodeling." (PMID 32015750, 2020).
anaplastic large cell lymphoma (6 papers, 2011 to 2025). Anaplastic large cell lymphoma (ALCL) is a rare and aggressive peripheral T-cell non-Hodgkin lymphoma, belonging to the group of CD30-positive lymphoproliferative disorders, which affects lymph nodes and extranodal sites. "In another PTCL subtype—anaplastic lymphoma kinase (ALK)-positive anaplastic large cell lymphoma (ALCL)—rearrangement of the ALK gene has also been shown to dysregulate the expression of Hypoxia-Inducible Factor (HIF-α) and subsequently VEGFA." (PMID 41295262, 2025).
ductal carcinomas (6 papers, 2008 to 2018). "Two closely linked SNPs in VEGFA were positively associated with ductal carcinoma." (PMID 28045923, 2017). "Additionally, the GeparQuinto study reported interactions between VEGFA SNPs and hormone receptor status, while our study indicated associations between VEGFA SNPs and ductal carcinoma, and FGF2 SNPs and receptor status." (PMID 28045923, 2017).
Dyskinesia (6 papers, 2014 to 2025). A movement disorder which consists of effects including diminished voluntary movements and the presence of involuntary movements. "When co-administered with L-dopa, the VEGFA inhibitor vandetanib significantly attenuated the development of L-dopa-induced dyskinesia." (PMID 33170152, 2020). "Chronic L-dopa therapy induces the overexpression of VEGFA in the corpus striatum and basal ganglia nuclei, further promoting the development of dyskinesias." (PMID 33170152, 2020). "However, long-term treatment with L-dopa has resulted in many VEGFA upregulation-related side-effects, such as dyskinesias." (PMID 33170152, 2020). "Treatment with VEGFA-targeted drugs could effectively preserve the curative effect of L-dopa while delaying the development of dyskinesia." (PMID 33170152, 2020).
endometrial tumors (6 papers, 2021 to 2025). "Recent studies have confirmed that VEGFA derived from epithelial and myeloid cells supports vascular remodeling in the endometrial tumor niche." (PMID 41331376, 2025).
human papillomavirus infection (6 papers, 2021 to 2025). "Pathway analysis of the genes annotated to the 11 CpG sites revealed enrichment in pathways related to Human papillomavirus infections, VEGFA-VEGFR2 signaling, and tight junction, which were reported to be related to the immune response to infections previously." (PMID 40629459, 2025). "The TNF, VEGFA, JUN, and IGF-1 genes and neuron death, PI3K-Akt, and human papillomavirus infection signalling pathways may possibly explain this association." (PMID 38977982, 2024). "The TNF, VEGFA, JUN, and IGF-1 genes and the neuron death, PI3K-Akt, and human papillomavirus infection signalling pathways may possibly explain this association." (PMID 38977982, 2024). "These GS genes were mainly enriched in receptor tyrosine kinase signaling, MET signaling, human papillomavirus infection, PDGF signaling, the VEGFA–VEGFR2 signaling pathway, and the EGF–EGFR signaling pathway." (PMID 39766034, 2024).
leishmaniasis (6 papers, 2018 to 2025). Infectious disease that is transmitted through the bite of hematophagous female phlebotomine sand flies. "Our in silico approach involved predicting the affinities of MIL and NMIL to critical proteins involved in leishmaniasis, including Vascular Endothelial Growth Factor A (VEGF-A), the Kinase insert domain receptor (KDR1), and apoptotic-regulator proteins (Bcl-2-associate)." (PMID 38291076, 2024).
membranous nephropathy (6 papers, 2015 to 2025). "Fourth, this study explored the relationship between VEGFA and PLA2R-associated IMN, but did not explore the relationship between VEGFA and secondary membranous nephropathy." (PMID 36114523, 2022).
metastatic prostate carcinoma (6 papers, 2012 to 2024). A carcinoma that arises from the prostate gland and has spread to other anatomic sites. "VEGFA expression was consistently elevated in metastases relative to normal samples, but treatment of metastatic prostate cancer with VEGF inhibitors typically fails." (PMID 26341082, 2015). "The predominant pro-angiogenic factor, VEGFA, is elevated in the plasma of patients with metastatic prostate cancer, but not in patients with localized primary prostate tumors." (PMID 26341082, 2015).